MIR199A2 (microRNA 199a-2)
Synonyms: hsa-mir-199a-2; MIR-199-s; MIRN199A2; mir-199a-2
Gene: MicroRNA gene on chromosome 1 (172,144,535 to 172,144,644, reverse strand). Ensembl gene ENSG00000208024.
Gene Ontology:
Biological process: miRNA-mediated post-transcriptional gene silencing
Cellular component: RISC complex
Homologues: Orthologues: chimpanzee ptr-mir-199a-2 (100% identical), macaque mml-mir-199a-1 (100% identical), guinea pig MIR199A2 (88% identical), pig MIR199A2 (85% identical), rat Mir199a2 (85% identical), mouse Mir199a-2 (84% identical), rabbit MIR199A2 (84% identical), tropical clawed frog xtr-mir-199a (81% identical), zebrafish mir199-3a (71% identical). Paralogues in human: MIR199B (64% identical), MIR199A1 (53% identical).